HIF1A (hypoxia inducible factor 1 subunit alpha)
Diseases named in the same sentence as HIF1A in open-access papers (continued):
Sharing a sentence is not in itself a finding about the gene and the disease.
tumor (continued). "HIF-1α knockdown was shown to block LRG1-mediated angiogenesis, EMT, and tumor invasiveness, and is consistent with LRG1 being induced in response to hypoxia." (PMID 38745756, 2024). "UALCAN and LinkedOmics databases were used to examine hypoxia-inducible factor 1-alpha (HIF-1α) expression and the relationship between studied genes and tumor clinical features." (PMID 39466438, 2024). "In tumor samples, the expression of IDH2, HIF1b, HIF2a, EGRF, PTEN and STAT3 was significantly downregulated, but HIF1a and VEGFC expressions were upregulated in U87MG STAT3 KO variant in comparison with U87MG cells." (PMID 38654280, 2024). "Various experimental models have shown a critical role for HIF-1α and HIF-2α in tumor progression and patient survival." (PMID 38571885, 2024). "The tumor tissue in the HI@Z/P/H+NIR and HIL@Z/P/H+NIR groups exhibited a mild higher HIF-1α expression than the control group, showing an aggravated hypoxia degree caused by the O2 consumption of PDT." (PMID 38280861, 2024). "In this study, we found that both HIF1α and α-SMA (CAFs-specific marker) were expressed at high levels in HNSCC tissues with lymph node metastasis, but the potential role of tumor-CAFs crosstalk under hypoxia in HNSCC metastasis is still unclear." (PMID 38485986, 2024). "This HIF-1α-mediated vascular remodeling results in a leaky vasculature within the TME, increasing plasma protein permeability, and promoting tumor growth and propagation." (PMID 38542288, 2024). "Of particular concern is the role of HIF-1α in tumor progression and metastasis, which requires cautious consideration in therapeutic interventions targeting the PHD2/3- HIF-1α axis." (PMID 39242595, 2024). "Prolonged hypoxia can activate HIF‐1a, which suppresses the activity of cytotoxic lymphocytes, such as NK cells and CD8+ T cells, thereby impeding their effectiveness in combating tumours." (PMID 38809929, 2024). "Our findings indicate that in EC patients having undergone NRCHT+R, the overall expression of FAK, HIF-1α, Ki67, and CD44 was higher in tumor nests, whereas ILK was higher in tumor stroma." (PMID 38727811, 2024). "The authors demonstrated that tumor environmental factors such as oxygen and nutrient deprivation induce the activity of AEP in a HIF1A-dependent manner." (PMID 38299588, 2024). "This synergistic effect of HIF-1α on VEGF results in increased mRNA levels and overexpression compared to other proteins in tumor cells." (PMID 38542288, 2024). "To have final confirmation of the role of HIF-1α in mediating the enhanced anti-tumor CD8 T-cell function in PHD2/3 KO CD8 T cells, we generated HIF-1α and PHD2/3 double knockout (double KO) OT-1 CD8 T cells and administered them to mice with MC38-OVA tumors." (PMID 39242595, 2024). "Clock components regulate the expression of angiogenesis factors in cancer cells, such as HIF1α, ARNT, and VEGF, promoting tumor growth and metastasis." (PMID 38678017, 2024). "Nanoparticles: Conventional methods of managing HIF-1α are invasive and systemically toxic but nanotechnology can deliver HIF-1α inhibitors directly to the site of tumor, thereby increasing drug availability and minimizing side effects." (PMID 39493156, 2024). "For example, miR‐497 was shown to target the HIF‐1a and VEGF, inhibit tumor growth and suppress angiogenesis in the BC." (PMID 38173189, 2024). "Remarkably, knocking down HIF-1α in OC cells significantly suppressed CAFs induced EMT and impeded tumor-promoting effects." (PMID 38491511, 2024). "Mechanistically, accumulated succinate inhibits the enzyme activity of HIF-1α prolyl hydroxylases (PHDs), allowing stabilized HIF-1α to form a complex with HIF-1β for the transcriptional activation of genes that support tumor growth." (PMID 38880883, 2024). "The SIRT4 binds to HIF-1α in a protein–protein interaction and directly inhibits HIF-1α expression, thereby blocking HIF-1α/HO-1-mediated tumor cell growth." (PMID 39876842, 2024).
tumor (continued). "HISLA can reduce the hydroxylation and degradation of HIF-1α via blocking the interaction between PHD2 and HIF-1α, which promotes glycolysis and lactate accumulation in tumor cells." (PMID 39539540, 2024). "Angiogenesis, the formation of new blood vessels, is driven by hypoxia-induced factors such as HIF-1α and VEGF, both of which play a crucial role in tumor growth and metastasis." (PMID 39595235, 2024). "Blocking adenosine receptor A2AR expressed on tumor cells can reduce Treg infiltration and facilitate CD8+ T cells’ anti-tumor ability through debilitating hypoxic HIF-1α signaling." (PMID 39188717, 2024). "In melanoma cell lines, transcriptional factor HIF-1a interacts with FLNACT and then is translocated into the nucleus to bind to the VEGF promoter to increase xenograft tumor progression and angiogenesis." (PMID 39195282, 2024). "Metformin has been found to possess the capability to diminish the production of HIF-1α via AMPK activation, leading to a decrease in tumor metastasis." (PMID 39101145, 2024). "Another target of SIRT2 is HIF-1α in the cytoplasm, promoting hydroxylation and degradation of HIF-1α, and inhibiting hypoxia-induced tumor growth." (PMID 39513038, 2024). "Keratin (multi KRT) and HIF1A, a key regulator of hypoxia adaptation, were upregulated in both p16+/HPV- and p16-/HPV- tumours relative to p16+/HPV+." (PMID 39328208, 2024). "Hypoxia activates hypoxia-inducible factors (HIFs), specifically, HIF-1α and HIF-2α, which regulate several pathways related to metabolism, angiogenesis, and tumor growth." (PMID 39335133, 2024). "EIF2 signaling is comprised of several endothelial cell transcription factors and regulates both cell cycle progression and angiogenesis, while ID1 signaling activates HIF-1a and VEGF-A to promote tumor angiogenesis in certain cancers." (PMID 38263175, 2024). "HIF1A stabilization was sufficient to induce an iCAFs phenotype in stromal cells introduced into PDAC organoid co-cultures and to promote PDAC tumor growth." (PMID 38892190, 2024). "In summary, our findings demonstrate that mRNA levels of HIF1A and hypoxia-related genes (CA9, VEGF, GLUT1) are increased in the tumor tissues of HNSCC patients compared to normal tissues." (PMID 38928200, 2024). "Studies indicate that downregulating HIF-1 expression by antisense HIF1-α enhances NK cell and CD8 T cell-mediated antitumor immunity, resulting in anti-tumor activity." (PMID 38994360, 2024). "HIF-1α stimulates the expression of VEGF and other pro-angiogenic factors, promoting tumor growth and metastasis." (PMID 39766169, 2024). "The results of IHC demonstrated that the expression of CDC37, GLA, HIF-1α and VPS35 was upregulated in the tumor tissues compared with corresponding normal tissues." (PMID 38528532, 2024). "Clinicopathologic data were collected from electronic medical records, and HIF-1α and GLUT-1 expressions were assessed in the tumor tissue." (PMID 39202223, 2024). "HIF‐1α and HIF‐2α have different roles in CRC, with HIF‐1α driving cancer development and HIF‐2α acting as a tumor suppressor." (PMID 39415849, 2024). "Propofol also inhibits tumor angiogenesis by downregulating HIF-1α and VEGF and suppresses tumor migration and invasion through the ERK 1/2 pathway and MMPs." (PMID 39766169, 2024). "This delivery system utilized the homologous targeting of tumor cell membranes to transport ACF, inhibiting HIF-1α expression, alleviating tumor hypoxia, and catalyzing ·OH production for effective tumor eradication." (PMID 38794281, 2024). "There is a main pathway involving the proteins of HIF-1α, VEGF, VEGFR2, PI3K, and AKT, relating to the tumor anti-angiogenesis, including the most flavonoids in our findings." (PMID 38611849, 2024). "The disadvantages of TACE include inducing the upregulation of HIF1-α and upregulating the expression of VEGF, fibroblast growth factor, or platelet-derived growth factor, followed by increasing tumor angiogenesis." (PMID 39451736, 2024).
tumor (continued). "Regarding gene amplification, EWSR1, FLT3, GPC3, HIF1A, HLF, and MEN1 have been reported in CaPa and other neoplasias as well." (PMID 38397997, 2024). "HIF-1α induces the expression of several immune checkpoint molecules, including PD-L1 and CTLA-4, on tumor cells and immune cells, respectively, thereby inhibiting T cell activation and promoting an immunosuppressive environment." (PMID 39457484, 2024). "Tumour cells regulate endothelial cells through the HIF1A‐VEGFA‐PLVAP axis, instigating angiogenesis and fueling tumour growth." (PMID 37994257, 2024). "Arsenic trioxide, an anticancer agent, disrupts the HIF-1α–VEGF–ANG axis by inhibiting PI3K-Akt/HIF-1α signaling, thereby limiting the paracrine activity of ANG 1 and ANG 2, resulting in the inhibition of angiogenesis and tumor growth." (PMID 38542288, 2024). "Lipid-polymer hybrid NPs loaded with si-HIF1α and gemcitabine (GEM) were constructed to investigate their synergistic anti-tumor effects." (PMID 38831883, 2024). "Conversely, HIF-1α inhibition can enhance T cell anti-tumor activity and inhibit glycolysis, and reducing HIF-1α levels in the TME can increase memory T cell production and improve anti-tumor function." (PMID 38327979, 2024). "Correlation of MRI—PET imaging and HIF-1α or VEGF immunophenotype has been reported, possibly allowing monitoring of tumor progression in vivo." (PMID 39055895, 2024). "CT26 mouse model was established to assess the synergistic effect of silencing HIF-1α combined with oxaliplatin (OXA) and imiquimod (IMQ) on tumor growth." (PMID 39614894, 2024). "More specifically, targeting CDK1 has shown efficacy in disrupting these pathways by inducing phosphorylation of HIF-1α or through lysosome-inducing degradation of HIF-1α, leading to reduced tumor growth and viability." (PMID 39697237, 2024). "Because RhoA/ROCK1 signaling is also closely related to tumor EMT and metastasis, we further investigated the role of HIF‐1α in DDR1‐induced EMT and metastasis in GC." (PMID 39024501, 2024). "The research further indicates that HIF1α expression is notably higher in triple-negative breast cancer (TNBC) and HER2-positive subgroups, suggesting its role in tumor aggressiveness and poor prognosis." (PMID 39697237, 2024). "Hypoxia has been found to induce expression of the protein PLOD2 in RCC via transcriptional activation by HIF1a; leading to downstream AKT activation and tumor progression." (PMID 39410010, 2024). "HIF-1α facilitates YAP activation by enhancing its expression and facilitating nuclear localization, thereby significantly promoting tumor cell proliferation, invasion, and differentiation." (PMID 39664389, 2024). "Increased IL-1β drives the further upregulation of HIF-1α in HCC cells, mediating an epithelial-to-mesenchymal transition (EMT), leading to more aggressive tumours and metastasis." (PMID 39684877, 2024). "Recent studies have confirmed that SIRT1 can promote angiogenesis via the deacetylation of HIF-1α and the regulation of VEGF expression, providing support for tumor growth and metastasis." (PMID 39845948, 2024). "J. K. Ahn reported that VBP1 elevates pVHL-induced HIF-1α ubiquitination, destabilizing HIF-1α and potentially inhibiting tumor metastasis." (PMID 38700744, 2024). "Histopathological evidence of HIF-1α and VEGF in tumor cells is presented along with the possible involvement in tumor prognosis, alongside cellular mechanisms, clinical and imaging analysis data, and therapeutic approaches." (PMID 39055895, 2024). "In conclusion, the effects of HIF-1α and HIF-2α on glutamine metabolism in tumor cells varies, as HIF-2α opposes HIF-1α and supports the progression of tumor cells." (PMID 38172980, 2024). "HIF-1α and HIF-2α, the two best-known hypoxia-activated transcription factors, share similar biochemical characteristics but exert differential effects on tumor cells in hypoxic environments." (PMID 38172980, 2024).
tumor (continued). "In addition, under hypoxia, EVs produced by MSCs scavenge ROS, induce M2 macrophage polarization, and stabilize HIF-1α in target cells, whereas EVs produced by ADSCs and umbilical cord-derived MSCs promote EC survival and angiogenesis, which may contribute to tumor progression." (PMID 39434182, 2024). "Overall, iRFA stimulates angiogenesis through the HIF‐1α/VEGF/VEGFR1 pathway, thereby accelerating tumor progression." (PMID 39359691, 2024). "DYB‐03 is a newly screened dual‐target compound that targeting both HIF‐1α and EZH2 and displays significant anti‐tumor activity in vitro and in vivo, indicating the potential for clinical combination target therapy." (PMID 38072662, 2024). "We analysed the changes in antioxidant (SOD1, SOD2, CAT, GPX1, HIF-1α, and NRF2) and anti-inflammatory nuclear factor kappa B (NF-κB) gene expression in tumour-bearing mice." (PMID 39506978, 2024). "Previous studies have reported that HIF-1α can interact with β-catenin to form HIF-1α/β-catenin complex, promoting tumor cell proliferation and metastasis." (PMID 38327979, 2024). "Immunohistochemical staining indicated HIF-1α positive expression, identified by the presence of brown staining in the nucleus and cytoplasm of VX2 tumor cells." (PMID 39872052, 2024). "Direct activation of HIF-1α in MDA-MB-231 cells in a xenograft model, showed a 3-fold reduction in tumour volume." (PMID 38352889, 2024). "Specifically, high levels of miR-210-3p were found to be accompanied by high levels of VEGF and CA9, while the transcription of VEGF and CA9 was found to be mediated by HIF-1α, implying high correlation of miRNAs to the hypoxia within the GBM tumor." (PMID 39055895, 2024). "Combinatorial treatment using the HIF-1α inhibitor Acriflavine and the Treg depletion agent Cytoxan improved CD8+ T cell responses and reduced tumor growth when compared to Acriflavine or Cytoxan alone." (PMID 38426087, 2024). "HIF-1α/HIF-2α correlated to a far greater extent with the two VEGF receptors and ETS-1 in the tumor tissue compared to the peritumor tissue, their level of association with VEGF-A was identical in both sample groups." (PMID 38607072, 2024). "HIF-1α also upregulates the expression of multi-drug resistance genes (ABCB1 and ABCC2), facilitating the efflux of drugs from tumor cells." (PMID 38879551, 2024). "The hypoxia-induced factor HIF-1α and VEGF play a crucial role in tumor angiogenesis and lymphangiogenesis." (PMID 38828455, 2024). "Another initial clinical study found that the expression of hexokinase II mRNA was increased in tumor tissue in some HCC patients pretreated with TAE, and hexokinase II mRNA expression was significantly correlated with HIF-1α protein expression." (PMID 39204162, 2024). "Hypoxia induces tumor angiogenesis, progression, and metastasis through the expression of VEGF and hypoxia-inducible factor 1α (HIF-1α)." (PMID 38927059, 2024). "A decrease in HIF-1α levels can also lead to a decrease in CD39 + and CD73 + immunosuppressive myeloid cells in the tumor microenvironment." (PMID 38286894, 2024). "The activation of HIF-1α in GBM promotes the differentiation and activation of Tregs, thereby facilitating tumor progression." (PMID 38893192, 2024). "HIF-1α and HIF-2α are overexpressed in cancer cells, which supports tumor growth by upregulating genes participating in tumor invasion and angiogenesis." (PMID 38339256, 2024). "In another study, hypoxia-mediated overexpression of HIF-1α increased the production and signaling of adenosine as well as protecting against drug-driven apoptosis in CLL cells, thus ultimately facilitating tumor progression." (PMID 37588219, 2024). "HIF-1α, VEGFA, and VEGFC have been reported to act as factors that contribute to tumour angiogenesis." (PMID 38035445, 2024). "During the process of OS cell proliferation, mitochondrial H2O2 signal transduction promotes tumor cell proliferation through HIF-1α-dependent and HIF-1α-independent manners." (PMID 38327979, 2024).
tumor (continued). "Immunohistochemical staining of tumor tissues showed that the expression levels of HIF-1α, VEGF, and MMP-9 decreased, which improved the hypoxic tumor microenvironment and inhibited tumor metastasis." (PMID 38951911, 2024). "NF90 is upregulated in various tumors, and its target mRNAs include HIF1α, PARP1, cyclin E1, TMEM98, VEGF, among others, suppressing the degradation of these target RNAs and inducing tumor proliferation, invasion, and angiogenesis." (PMID 39420007, 2024). "Particularly, in HCC the IDO upregulation by pDCs was mediated by HIF-1α/CCL20/STAT1 pathway, promoting tumor tolerance and metastatization." (PMID 39020402, 2024). "HIF-1α, an important biomarker of the hypoxic TME, contributes significantly to the survival of tumor cells and to resistance to radiochemotherapy (RCHT)." (PMID 38727811, 2024). "Their work discovered that hypoxia increases the expression of hypoxia‐inducible factor 1 alpha (HIF‐1α) in MSCs, thereby enhancing their ability to migrate toward tumor cells." (PMID 39070181, 2024). "On the other hand, in cancer therapy directed against HIF-1α and VHL, it shows important effects, decreasing tumor growth and cancer progression." (PMID 38921041, 2024). "Here authors deleted the prolyl hydroxylase domain-containing enzymes PHD2 and 3, thereby stabilizing HIF-1α, in therapeutic CD8 T cells to achieve better functionality upon adoptive transfer to tumour-bearing mice." (PMID 39242595, 2024). "Transcription factor activity assays revealed that the new inhibitors effectively blocked the activity of NF-κB, HIF1α, and STAT3 in PDAC tumor cells, with dose-dependent reductions in transcription factor activity observed." (PMID 39635662, 2024). "Taken together, these results suggest that Scu inhibits HIF1a-induced acidification of the tumor cell environment by activating IDH1, thereby activating the immune microenvironment of tumor cells." (PMID 38622131, 2024). "This includes inhibiting the infiltration of leukocytes into tumor tissues, reducing HIF-1α expression, as well as downregulating the proinflammatory enzymes COX-2 and iNOS in tumor tissues." (PMID 38611849, 2024). "The reduced hypoxia leads to lower HIF‐1α levels, decreasing SLC7A11 subunit activity, impeding GSH synthesis, and reducing tumor cell resistance to ferroptosis." (PMID 38867396, 2024). "This, in turn, reduces HIF-1α levels, thus making EZN-2208 potentially useful in the treatment of tumor growth and progression." (PMID 39493156, 2024). "In conclusion, NK cells, T cells, and their associated pathways were activated in the immune‐related anti‐tumor process of PDEH, while M2 macrophages and HIF‐1α decreased." (PMID 39118566, 2024). "The activation of PKM2 in hypoxic BC cells leads to the activation of NF-κB/p65 and HIF-1α, resulting in increased production and secretion of vascular endothelial growth factor (VEGF), which promotes angiogenesis and tumor growth." (PMID 39411137, 2024). "Taken together, our results highlight T cell HIF1α-anaerobic glycolysis as a principal mediator of IFN-γ induction and anti-tumor immunity." (PMID 38260594, 2024). "In addition, HIF-1α and HIF-3α nuclear expression levels were significantly associated with CSS in patients with ccRCC in univariate analysis but not HIF-2 α, implying that the major HIF-α proteins have different biological features that are crucial for tumor progression." (PMID 38571885, 2024). "In particular, the pDC recruitment to the tumor site and upregulation of IDO were mediated by HIF-1α/eADO/ADORA1 signaling." (PMID 39020402, 2024). "After HBO treatment, the expression of hypoxia-inducible factor-1α (HIF-1α) decreased, indicating that HBO overcame the tumor hypoxia." (PMID 38886343, 2024). "The tRNA methyltransferase 9-like protein (hTRM9L/KIAA1456) inhibits tumor growth via Lin-9 DREAM MuvB core complex component (LIN9) and hypoxia-inducible factor 1 subunit alpha (HIF1α)-dependent mechanisms." (PMID 38339348, 2024).